GPER1 (G protein-coupled estrogen receptor 1)
Diseases named in the same sentence as GPER1 in open-access papers (continued):
Sharing a sentence is not in itself a finding about the gene and the disease.
tumor (continued). "Therefore, there is a negative correlation between the expression of GPER1 in macrophages and their proliferation, both in vitro and in HCC tumor tissues." (PMID 39582864, 2024). "At 100 mg/kg bw/day, BPAF resulted in the significant upregulation in gene expression of seven targets (GPER1, JNK, Akt, Fos, FOXO1, PDZK1, SRF), while the gene expression of the other 12 targets were not significantly changed compared to the SK-BR-3 bearing tumor control." (PMID 36497816, 2022). "We could not observe a role of estrogens or GPER1 in cell proliferation (i.e., under normoxic conditions), but we did show an effect on key CRC lesions, that is, CA and w-CIN that may contribute to tumorigenesis, tumor progression, or therapy resistance." (PMID 36384894, 2023).
cardiovascular diseases (15 papers, 2013 to 2025). "Although GPER1 is largely viewed as a promising therapeutic target in the treatment of cardiovascular disease, we would argue that its effects are currently incompletely understood, meriting further investigation." (PMID 36085551, 2023). "Increasing evidence suggests potent protective effects of G-protein coupled estrogen receptor 1 (GPER) activation against cardiovascular diseases." (PMID 23840305, 2013).
metabolic disorders (12 papers, 2019 to 2026). "Considering that both GPER1 and nuclear ERs mediate the beneficial effects of E2 on metabolic disorders, we further investigated the contribution of nuclear ERs, including ERα and ERβ, to the beneficial metabolic outcomes observed in PO-induced L02 cells and HepG2 cells." (PMID 38246352, 2024). "cAMP is a positive mediator of multiple metabolic regulations, and the identification of AC as the target of GPER1 might explain the beneficial regulatory effect of GPER1 on metabolic disorders." (PMID 38246352, 2024). "G protein-coupled estrogen receptor 1 (GPER1) exerts hepatic protective effects, and GPER1 specific agonist (G1) has shown preclinical potential in improving metabolic disorders." (PMID 41929249, 2026). "Therefore, we subsequently generated the hepatic-specific GPER1 knockout (GPER1-HKO) mouse to certify the role of hepatic GPER1 in the protective effect of estrogen against metabolic disorders in OVX female mice with or without subcutaneous implantation of E2-sustained release tablet." (PMID 38246352, 2024).
kidney disease (5 papers, 2021 to 2023). "Emerging evidence suggests that GPER1 signaling regulates oxidative stress, a major player in the pathogenesis of aging and cardiovascular and renal disease." (PMID 35327604, 2022). "GPER1 has been shown to be protective against CV and renal diseases in different experimental animal models." (PMID 35327604, 2022). "The purpose of this review is to outline current understanding of GPER1-mediated actions and signaling pathways that may play a role in cardio-renal disease." (PMID 35327604, 2022). "Understanding the mechanisms by which GPER1 could impact ROS could provide additional targets for therapeutics in the treatment of CV and renal diseases." (PMID 35327604, 2022). "A better understanding of the mechanisms by which GPER1 could impact inflammation and immune infiltration could provide additional targets for therapeutics in the treatment of CV and renal diseases." (PMID 35327604, 2022). "Improving our understanding of how GPER1 impacts the RAAS system, particularly aldosterone non-MR signaling, could provide targets for management of blood pressure and water and electrolyte balance, which are often dysregulated with CV and renal diseases." (PMID 35327604, 2022).
neurodegenerative disease (3 papers, 2018 to 2025). A disorder of the central nervous system characterized by gradual and progressive loss of neural tissue and neurologic function. "G protein-coupled receptor 30 (GPR30, also known as Gper1) is an estrogen-binding receptor that has shown therapeutic benefits in patients with certain degenerative diseases." (PMID 40076648, 2025).
infectious disease (2 papers, 2019 to 2024). A disorder directly resulting from the presence and activity of a microbial, viral, or parasitic agent in humans. "GPER1 activation mitigates pathogenesis in a mouse model of Staphylococcus aureus skin infections, reinforcing the role of estrogen in supporting innate immunity against infectious diseases via GPER1." (PMID 39684286, 2024).
bacterial infection (1 paper, 2024). "Moreover, in spring, bacterial infection also caused an upregulation of the expression of genes encoding for membrane estrogen receptor GPER1 and CYP19 (24 hpi) in the liver." (PMID 38157099, 2024).
hematological malignancies (1 paper, 2023). "In the context of hematological malignancies, the role and the therapeutic potential of GPER1-targeting have been less investigated." (PMID 37759449, 2023).
retinopathy (1 paper, 2022). "Multivariate regression analysis was performed to assess the researchers’ model,which considers GPER-1 (a possible retinopathy preventative) alongside age, sex anddiabetes duration (factors known to influence DR development)." (PMID 35857982, 2022).
GPER1 also shares sentences with these, for which no sentence is quoted: cardiac hypertrophy (9 papers); glioblastoma (9); inflammatory bowel disease (8); colitis (7); invasive breast carcinoma (7); germ cell tumor (6); infection (6); ovarian endometriosis (6); adenocarcinoma (5); Hypoglycemia (5); osteoporosis (5); pancreatic ductal adenocarcinoma (5); Stroke (5); testicular tumors (5); adenomyosis (4); benign prostate hyperplasia (4); cognitive decline (4); Crohn disease (4); dysplastic nevi (4); experimental autoimmune encephalomyelitis (4); Leydig cell tumor (4); mesothelioma (4); Myocardial fibrosis (4); pancreatic adenocarcinoma (4); testicular seminoma (4); -dependent (3); Arthritis (3); breast (3); cardiac arrest (3); cervical adenocarcinoma (3).
A further 183 diseases each share a sentence with GPER1 in 3 papers or fewer.